MAD2L1BP (MAD2L1 binding protein)
Description:
May function to silence the spindle checkpoint and allow mitosis to proceed through anaphase by binding MAD2L1 after it has become dissociated from the MAD2L1-CDC20 complex.
Synonyms: CMT2; KIAA0110; dJ261G23.1; p31comet
Tractability: Small molecule: a structure with a bound ligand is known. PROTAC: ubiquitination databases record sites on it.
Gene: Protein-coding gene on chromosome 6 (43,629,494 to 43,640,955, forward strand). Ensembl gene ENSG00000124688.
Subcellular location: Nucleus; Cytoplasm, cytoskeleton, spindle
Subcellular location (Human Protein Atlas): Nucleoli; Nucleoplasm; Nuclear membrane
Gene Ontology:
Molecular function: protein binding
Biological process: deactivation of mitotic spindle assembly checkpoint; regulation of exit from mitosis
Cellular component: cytoplasm; nuclear membrane; nucleolus; nucleoplasm; nucleus; spindle
Genetic constraint (gnomAD): Loss-of-function variants: 22 observed, 29.34 expected, observed/expected ratio (o/e) 0.75, 90% interval 0.54 to 1.07. The upper end of that interval is the gene's LOEUF score, 1.07, which puts it in group 4 of 6, group 1 being the genes least tolerant of losing a copy. Missense variants: 325 observed, 358.81 expected, observed/expected ratio (o/e) 0.91, 90% interval 0.83 to 0.99. Synonymous variants: 146 observed, 137.82 expected, observed/expected ratio (o/e) 1.06, 90% interval 0.93 to 1.22.
Homologues: Orthologues: macaque MAD2L1BP (95% identical), chimpanzee MAD2L1BP (93% identical), dog MAD2L1BP (88% identical), pig MAD2L1BP (86% identical), rabbit MAD2L1BP (81% identical), guinea pig MAD2L1BP (80% identical), rat Mad2l1bp (80% identical), mouse Mad2l1bp (77% identical), tropical clawed frog MAD2L1BP (46% identical), zebrafish mad2l1bp (35% identical), Drosophila melanogaster CG13599 (16% identical).
Diseases named in the same sentence as MAD2L1BP in open-access papers:
MAD2L1BP is named in the same sentence as 10 diseases in open-access papers, as found by Europe PMC text mining. Sharing a sentence is not in itself a finding about the gene and the disease. The quoted sentences say what the papers report.
brain malformations (1 paper, 2023). "Since phenotype severity may apparently vary significantly even between siblings (patient 1b has less pronounced brain malformations than his sister and no psychomotor impairment), phenotypes may be even more variable between unrelated carriers of biallelic pathogenic MAD2L1BP variants." (PMID 37796616, 2023).
Epileptic encephalopathy (1 paper, 2023). A condition in which epileptiform abnormalities are believed to contribute to the progressive disturbance in cerebral function. "We report on 3 patients from 2 families with homozygous MAD2L1BP nonsense variants and microcephaly, epileptic encephalopathy with brain malformations, and impaired growth and psychomotor development." (PMID 37796616, 2023). "Another homozygous truncation, R227*, detected in an early-deceased patient with low-level aneuploidy, severe epileptic encephalopathy, and frequent blood glucose elevations, likely corresponds to complete loss of function, as in Mad2l1bp–/– mice." (PMID 37796616, 2023). "We identified a homozygous MAD2L1BP nonsense variant, R253*, in 2 siblings with microcephaly, epileptic encephalopathy, and juvenile granulosa cell tumors of ovary and testis." (PMID 37796616, 2023).
female infertility (1 paper, 2023). Diminished or absent ability of a female to achieve conception. "Together, these results reinforced the detrimental effect of MAD2L1BP variant on SAC silence accounting for female infertility." (PMID 37334967, 2023).
gastric cancer (1 paper, 2012). A primary or metastatic malignant neoplasm involving the stomach. "Novel genes included SIAHBP1ATP6V1C1SLC25A32ZFAND1MCM4XPO5PLOD3PSMA7EIF3S6TPD52NSMCE2MRPS18ASTK3, and MAD2L1BP with no previous gastric cancer associated reports." (PMID 22559327, 2012).
Hypoglycemia (1 paper, 2023). A decreased concentration of glucose in the blood. "However, Mad2l1bp-deficient mice died perinatally owing to the neonatal hypoglycemia resulting from the liver glycogen shortage, rendering us fail to get the homozygous KI offspring." (PMID 37334967, 2023).
microcephaly (1 paper, 2023). A congenital or acquired developmental disorder in which the circumference of the head is smaller than normal for the person's age and sex. "We identified a homozygous MAD2L1BP pathogenic nonsense variant (R253*) in 2 siblings with microcephaly, brain malformations (with cysts and polymicrogyria), seizures, developmental delay, and juvenile granulosa cell tumor (JGCT) of ovary and testis, respectively." (PMID 37796616, 2023).
bacterial infections (1 paper, 2022). "Comparison of these results with those obtained from bacterial infections showed genes associated with cell‐cycle progression and cell proliferation (RGCC, SENP5, SMC6, SERTAD3, MAD2L1BP) to be specifically upregulated in DC3s." (PMID 34333764, 2022).
MAD2L1BP also shares sentences with these, for which no sentence is quoted: cancer (3 papers); granulosa cell tumor (1); lung carcinoma (1).